KRAS (KRas proto-oncogene, GTPase)
Diseases named in the same sentence as KRAS in open-access papers (continued):
Sharing a sentence is not in itself a finding about the gene and the disease.
tumor (continued). "Integration of DDR-targeted agents with TME-modulating therapies, such as KRAS inhibitors, myeloid/CD11b modulators, or CAF-directed approaches, may enhance T cell infiltration and anti-tumor response." (PMID 40951294, 2025). "Therefore, combining adagrasib and SHP2 inhibitors would prevent KRAS from reloading with GTP, resulting in more substantial and sustained tumor growth inhibition." (PMID 40805153, 2025). "Studies show that mutant KRAS promotes epithelial cell proliferation and tumor stemness more effectively, partly by suppressing non-canonical Wnt signaling." (PMID 40805153, 2025). "A multi-institutional analysis of repeat tumor or plasma biopsies from patients with RET fusion-positive NSCLC treated with selpercatinib and pralsetinib identified the emergence of MET amplification (15%) and KRAS amplification in one case each." (PMID 39850629, 2025). "Furthermore, we have shown significant intracranial activity of adagrasib in BM mouse models of KRAS-G12C NSCLC, and preliminary but encouraging anti-tumor effects with effective cerebrospinal fluid (CSF) penetration in patients with KRAS-G12C BM." (PMID 40317086, 2025). "Notably, both WT‐KRAS (G12D) mice and Med23−/−‐KRAS (G12D) mice receiving CD103+ T cells exhibited a significant decrease in tumor number compared with the mice that received CD103− T cells." (PMID 40344646, 2025). "In contrast, efficacy was limited in tumors such as KRAS-mutated NSCLC, likely because these tumor cells are not addicted to ERK1/2 signaling or can compensate for its inhibition via alternative pathways (NCT02972034)." (PMID 40723336, 2025). "Subsequent hallmark pathway analysis indicated increase of epithelial mesenchymal transition (EMT) and cancer stem cell-regulating pathways, such as Wnt/beta-catenin signaling, KRAS signaling, TGF-β signaling, AKT signaling, etc., in the basal subgroup of tumor cells." (PMID 40670350, 2025). "Additionally, their drug was able to inhibit tumor growth in both subcutaneous and orthotopic xenograft mouse models inoculated with tumors from patients with PDAC KRASG12D and KRAS- that had relapsed after chemo- or radiotherapy." (PMID 40002297, 2025). "Complementing these mechanisms, in KRAS-driven malignancies, suppression of the type I interferon (IFN) pathway emerges as a critical mechanism of tumor immune evasion, with pathway inactivation demonstrating strong correlation with concurrent activation of oncogenic signaling networks such as MYC." (PMID 40303413, 2025). "The comutation of KRAS and LKB1 elevated the expression of the lactate transporters in tumor cells." (PMID 40485603, 2025). "While these inhibitors have been shown to elicit tumor regression in MMTV-v-HRAS mice, they have yet to induce significant tumor regression in KRAS driven tumors and have not been tested in bAVMs." (PMID 39899215, 2025). "Given that KRAS mutations are known to reprogram glucose and glutamine metabolism to support tumor growth, RASON may indirectly influence these metabolic pathways by sustaining oncogenic KRAS activity." (PMID 40558487, 2025). "For example, siRNA targeting mutant KRAS is effective in inhibiting tumor cell proliferation without affecting normal cells." (PMID 40390497, 2025).
tumor (continued). "FoundationOne next-generation sequencing showed that her PD-L1 tumor proportion score was 0%, tumor mutation burden was low, and there were no reportable alterations in BRAF, ERBB2, KRAS, or NRAS." (PMID 40026534, 2025). "CT-26 do not express a mutation at the KRAS locus (wild-type) and are MSS/MMR-p, modeling an immune cold tumor phenotype." (PMID 40013140, 2025). "Under high oxidative stress conditions within the tumor microenvironment, pancreatic ductal adenocarcinoma (PDAC) tumor cells secrete the KRAS G12D protein, which in turn stimulates fatty acid oxidation in macrophages and facilitates their polarization towards the M2-type through the STAT3 pathway." (PMID 38853203, 2024). "No recurrent mutations, such as mutations in EGFR, KRAS, or AKT genes, were present in our tumor samples." (PMID 39199663, 2024). "The percentage of NK cells in the KRAS mutant group was higher than in the wild type (WT) regardless of in stroma, tumor, or stroma plus tumor." (PMID 38292189, 2024). "No oncogenic drivers were identified (analysis performed on tumor tissue sample through polymerase chain reaction testing EGFR and KRAS mutations)." (PMID 38392077, 2024). "A recent study concluded that autophagy is not essential in KRAS‐mutant tumor cells, despite its necessity for tumorigenic growth." (PMID 39436197, 2024). "Mutations in the KRAS gene are prevalent in approximately 90% of PDAC cases, irrespective of tumor stage." (PMID 39200178, 2024). "Both KRAS‐mutant HPAF‐II and MIA PaCa‐2 (MIA) cell xenografts were refractory to AZD4573, with average tumor growth inhibition (TGI) rates of 58% and 27%, respectively, compared to 97% in an acute myelocytic leukemia (AML) cell xenograft model (MV‐4‐11) under the same treatment condition." (PMID 39254172, 2024). "Unlike many tumor-associated antigens (TAA), KRAS is classified as a TSA, meaning it is only expressed in tumor cells and does not cause on-target off-tumor side effects." (PMID 38752985, 2024). "Focal Adhesion Kinase (FAK) acts as a mediator in sustaining KRAS-driven lung tumors, and although FAK inhibitors are currently undergoing clinical development, clinical data indicated that their efficacy in producing long-term anti-tumor responses is limited." (PMID 39271958, 2024). "KRAS also stimulates the hexosamine biosynthesis pathway (HBP) and the non-oxidative arm of the PPP through MAPK-dependent signaling cascades, ultimately facilitating tumor survival." (PMID 38921460, 2024). "MRTX1133 is a selective and non-covalent KRAS G12D inhibitor and has shown anti-tumor efficacy in vivo and in vitro models, especially in KRAS G12D mutant PDAC models." (PMID 38756650, 2024). "ROCK signaling has been shown to be upregulated in KRAS mutant NSCLC cell lines, animal models, and tumor tissues derived from patients, and it is thought that the increased stiffness of the extracellular matrix of the tumor, combined with hypoxia, activates the RhoA/ROCK pathway." (PMID 38921484, 2024). "While recapitulating many features of human NSCLC, KRAS mutant GEMMs differ in that they are unable to evoke strong anti-tumor immune responses, thus potentially lacking patient faithful responses to pharmacological intervention." (PMID 39533328, 2024). "Perhaps because of this negative regulation, YAP was reportedly not induced by oncogenic Ras in a mouse model of KRAS-driven lung cancer, even though it was still required for tumor formation." (PMID 39518045, 2024). "In KRAS-mutant NSCLC cell lines, avutometinib also demonstrated synergistic activity in reducing tumor cell viability when combined with other agents, including sotorasib, adagrasib, the focal adhesion kinase inhibitor defactinib, and the mTOR inhibitor everolimus." (PMID 39337530, 2024).
tumor (continued). "Let-7 targets multiple oncogenes (RAS, c-MYC, HMGA2 to date) and the prominent mechanisms by which let-7 exerts a tumor suppressive role is by repressing the translation of the three RAS proteins (HRAS, NRAS, and KRAS) and c-MYC, a downstream effector of RAS-ERK signaling." (PMID 38637419, 2024). "For instance, 23% and 33% of non-squamous NSCLC had point mutations in KRAS and EGFR, respectively, consistently detected by all three platforms, except in case AB, which had 32% tumor content." (PMID 38398180, 2024). "There are potential reasons why current treatments are not highly effective in treating SMARCA4/KRAS NSCLC co-mutations, as the tumor microenvironment (TME) plays an important role in metastatic NSCLC." (PMID 39063938, 2024). "Screening for KRAS, while very important for early detection, is not limited to PC alone, leaving an open question of which tumor is contributing to the detection." (PMID 39409171, 2024). "Moreover, upregulation of E2F activity was exhibited upon the characterisation of deregulated CRC KRAS mutant tumours and CIN type tumours." (PMID 39348343, 2024). "In contrast, in this preclinical model the combination of KRAS(ON) G12C-selective and SHP2 inhibitors significantly extends survival, suggesting that patients with immune evasive tumours may obtain greater benefits from this combination." (PMID 39322643, 2024). "Imbalanced TEADs transcriptional output leads to the signal enhancement of many oncogenes, including KRAS, BRAF, LKB1, NF2, and MYC, and subsequently facilitates tumor progression, metastasis, cancer metabolism, and immunity, and serving as the hallmark of cancer." (PMID 38607003, 2024). "Anti-tumor efficacy was not seen in NSCLC cells with mutations in those genes, indicating that EGFR and KRAS mutation status can be predictive markers of response to IGF-1R TKIs." (PMID 38540176, 2024). "Genomic testing revealed a KRAS, NRAS, BRAF wild type and a dMMR tumor." (PMID 39064004, 2024). "The effects of autophagy on KRAS‐induced tumorigenesis were not adequate to induce tumor transformation." (PMID 39436197, 2024). "Since KRAS and BRAF are known regulators of metabolism in multiple cancers, driving rewiring in tumour cells, CIMP tumours could harbour a particular metabolic signature, differentiating them from other types of CRCs." (PMID 38540202, 2024). "In patients without tissue profiling EGFR ex19del, EGFR L858R and KRAS G12/G13 mutations were detected by ddPCR in two, one and ten patients, respectively, corresponding to 7.1% of all patients without NGS of tumour tissue." (PMID 39083479, 2024). "Besides its role in tumorigenesis, the Hippo pathway plays a pivotal role in drug resistance of NSCLC via crosstalk with other well-known tumor-promoting factors such as EGFR, ALK, BRAF, KRAS, and ROS1." (PMID 38499647, 2024). "Spearman correlation test showed that tumor size and KRAS VAF were not correlated (ρ = 0.275, P = 0.082)." (PMID 38525415, 2024). "Despite the role of KRAS and BRAF in driving the CIMP phenotype and rewiring cancer metabolism, few studies have aimed at establishing whether CIMP tumours have a different metabolism." (PMID 38540202, 2024). "LUNG37 received immunotherapy based on PD-L1 tumor expression and a lack of access to KRAS targeted therapy at the time." (PMID 39195317, 2024). "Similarly, SIRT2 contributes to tumorigenesis by regulating KRAS acetylation and MYC stability, while influencing the inflammatory responses that shape the pro-tumor microenvironment." (PMID 39682281, 2024). "Next-generation sequencing (NGS) identified KRAS G12V and PTCH1 E340V mutations, and immunohistochemical (IHC) staining indicated negative PD-L1 expression (tumor proportion score, TPS < 1%)." (PMID 38659041, 2024).
tumor (continued). "However, KRAS is a known regulator of MDSC recruitment also in early PC lesions, mediating the release of GM-CSF by tumor cells." (PMID 39020414, 2024). "Comparing different KRAS alterations, tumors with KRAS G12D (6.2 mut/Mb), G12A (8.6 mut/Mb), G12V (8.6 mut/Mb), and Q61H (7 mut/Mb) alterations had the lowest TMB among tumors with KRAS alterations (<10 mut/Mb) and significantly lower TMB than all other tested KRAS tumor groups (≥10 mut/Mb)." (PMID 39664186, 2024). "A lower score of the KRAS signaling is expected in the necrotic edge, assuming that the tumor cells in this niche are not actively proliferating." (PMID 38744956, 2024). "A recent analysis of >600 patients with metastatic PDAC found significantly worse OS when KRAS G12C was detected in a patient’s tumor versus KRAS negative." (PMID 38982051, 2024). "Based on the other somatic variants observed, we estimated that 2 of the 4 samples without detectable KRAS did contain tumor material at a useful cellularity." (PMID 39123450, 2024). "There was no significant impact of primary tumor location, metastatic site, or KRAS status on PFS and OS." (PMID 38893113, 2024). "Therapeutically, ASOs and siRNA targeting oncogenes like HER2, KRAS, and VEGF, as well as lncRNAs such as HOTAIR and MALAT1, and circRNAs like circPVT1 and circ_0000523, can inhibit cancer-promoting pathways and reduce tumor growth and metastasis." (PMID 39857631, 2024). "In other words, mutations in Ras genes (such as KRAS and NRAS) or BRAF genes can activate downstream signaling pathways without EGFR inhibition, leading to tumor proliferation." (PMID 38342905, 2024). "Moreover, expression of mutant KRAS was shown to upregulate FSP1 in an NRF2-dependent manner, which in turn leads to increased ferroptosis resistance and increased tumor initiating capacity." (PMID 38908072, 2024). "Instead, a single dichotomized biomarker where patients with high EREG and high AREG are combined was found to be predictive of panitumumab response rate and survival benefit in KRAS WT patients independent of BRAF mutational status and primary tumor location." (PMID 40727266, 2024). "We observed positive correlations between the expression level of TRIM1and the CRC tumor stage, the EMT signaling, and two malignant tumor marker genes Ki67 and KRAS, implying that TRIM1 may play a promotive role in CRC tumorigenesis." (PMID 38769340, 2024). "Compared to 20 KRAS WT, the expression level of SURF6 is higher in the 20 KRAS mutant CRC tumor." (PMID 39523457, 2024).
tumor (continued). "The specificity of mutant-specific KRASG12C inhibitors for mutant KRAS in cancer cells without inhibiting wild-type KRAS in normal cells has helped to define the role of oncogenic KRAS signalling in modulating anti-tumour immune responses." (PMID 39322643, 2024). "Indeed, let-7 inhibits LC tumor growth by targeting c-MYC, KRAS and HMGA2, binds to DICER, i.e., a RNAase which processes miRNAs, and induces cell autophagy in LC." (PMID 38245882, 2024). "scRNA-seq analysis confirmed the presence of copy number variations (CNVs) and KRASG12D mutations in patient-specific tumour clusters and the absence of KRASG12D in KRAS wild-type LUADs (KW-LUADs)." (PMID 38418883, 2024). "In line with our human data, Krt8high KACs with increased expression of KAC and KRAS signatures were enriched in ‘reactive’, non-neoplastic regions surrounding tumours and were themselves intermediary in the transition from normal to tumour cells." (PMID 38418883, 2024). "Though there is a co-existence of KRAS mutation and other RAS-effector mutations in the same tumor, KRAS and BRAF mutations do not occur in the same tumor." (PMID 39056802, 2024). "Moreover, increased levels of KRAS, ATR, and CHEK proteins correlated with a high rate of tumor cell proliferation and aneuploidy in ECE cases with metastatic lesions following primary tumor resection." (PMID 38669256, 2024). "Predictors of positive response to cetuximab therapy include tumor overexpression of EGFR and absence of mutations in the KRAS gene." (PMID 38769503, 2024). "Consequently, KRAS*‐STAT4‐mediated upregulation of the Y chromosome KDM5D contributes significantly to sex differences in KRAS*CRC by disrupting cancer‐cell adhesion properties and tumor immunity." (PMID 38222317, 2024). "Further investigation of the ovarian histology was conducted, and the results were negative for the following tumor mutations: PIK3CA, KRAS, IDH1, and BRAF." (PMID 39816315, 2024). "Moreover, key signaling pathways including Kirsten rat sarcoma viral oncogene (KRAS), transforming growth factor beta (TGF-β), Notch, hypoxia-inducible factor (HIF), and Wnt/β-catenin drive tumor progression and resistance." (PMID 39001498, 2024). "In Case 3, which had the lowest tumour content (10–15%), a PMS2 mutation was found suggesting that the lack of KRAS mutation in this sample is a genuine finding." (PMID 38762572, 2024). "Additionally, research has shown that tumor markers like CEA, SUV uptake value on PET CT, poor performance status (PS), tumor spread through air spaces (STAS), and molecular parameters such as the Ki-67 and KRAS status can influence OS and DFS." (PMID 39202654, 2024). "Clinical trials in patients with KRAS mutations suggest that, although highly promising, FAK inhibitors do not provide a durable anti-tumor response." (PMID 39271958, 2024). "The PNI score indicated that KRASG12D‐related PDAC was associated with increased nerve density and severity of PNI compared to other KRAS subtypes, whereas inhibition of EV secretion in Rab27a‐knock out (KO) mice suppressed the severity of neural infiltration in PANC‐1‐induced tumor tissues." (PMID 39488792, 2024). "Genetic testing revealed no mutations in common oncogenes, such as KRAS, BRAF, or PIK3CA, supporting the borderline nature of the tumor." (PMID 39816315, 2024).